CRP (C-reactive protein)
Diseases named in the same sentence as CRP in open-access papers (continued):
Sharing a sentence is not in itself a finding about the gene and the disease.
tumor (continued). "The most reliable factors in determining PDAC patient survival are, therefore, clinical parameters such as TNM stage, tumour grade, margins of resection and pre- and postoperative levels of C-reactive protein (CRP) and CA-19-938." (PMID 33828170, 2021). "A recent study showed that pathological C-reactive protein and a tumor with an unfavorable diagnosis were poor prognostic factors for 1-year survival in patients undergoing surgery for long bone metastases." (PMID 34404379, 2021). "The correlation analysis in CRLM patients revealed that pretreatment CRP was positively correlated with the location of the primary tumor, and pretreatment CEA and CA19-9." (PMID 34765598, 2021). "CRP can also predict tumor response to ICI treatment, and plays an important role in the prediction of immune-related adverse events." (PMID 34859069, 2021). "This study demonstrates that a pre-operatively elevated serum CRP level in surgically resected patients is an important prognostic factor for survival independent from tumour differentiation and tumour stage." (PMID 34887479, 2021). "In conclusion, we provide the first evidence for CRP as an enhancer of in vitro IgG-mediated erythrocyte and tumor cell destruction." (PMID 33790888, 2021). "If the tumor is regarded as “a battle,” CRP can reflect the intensity of the battlefield and the lethality of weapons, while MCV is a fortress against damage." (PMID 34221966, 2021). "The authors report significantly higher serum CRP levels in older patients (≥ 60 years), tumours ≥ 3 cm and G3 differentiated patients." (PMID 34887479, 2021). "Some cytokines that are involved in inflammation response, including IL‐1β, IL‐6, TNF, and C‐reactive protein (CRP), are increased in depressed patients and promote tumor progression." (PMID 34723436, 2021). "In univariable sensitivity analyses CRP was confirmed as a prognostic factor for overall survival in subgroups with G2 differentiation, T1/T2 and T3/T4 tumour stages, patients with node positive disease and with and without distant metastases." (PMID 34887479, 2021). "In T3 and T4 tumours median OS was 166 months, 69 months and 17 months for normal serum CRP values, CRP 5-20 mg/l and CRP > 20 mg/l, respectively." (PMID 34887479, 2021). "CRP acts on the microglia through IL-1β, which protects endothelial cells from starvation-induced death and thereby contributes to tumor angiogenesis and progression." (PMID 33747971, 2021). "The relationship between inflammatory indexes such as TLC, NLR and CRP and tumor short-term and long-term prognosis has attracted more and more attention." (PMID 34666774, 2021). "Of note, differences in neutrophil counts and CRP are well‐known prognostic factors for patients with tumor diseases." (PMID 34121360, 2021). "Inflammatory markers such as CRP, TNF-α, and IL-6 are associated with higher tumor grade and risk of mortality in CRC patients and are elevated in the blood of CRC patients compared to healthy controls." (PMID 34239993, 2021). "Serum leptin levels on day seven were correlated significantly to sex (p = 0.004), distant metastases (p = 0.019), patients’ BMI (p = 0.002), tumour grade (p = 0.033) and serum CRP levels on day one (p = 0.027)." (PMID 34827598, 2021). "Our final nomogram included five independent risk factors, liver function parameters: ascites (C-index: 0.606) and γ-GGT (C-index: 0.596); inflammatory indicator: CRP (C-index: 0.596); and a tumor-related index: HGB (C-index: 0.604) and PVTT (C- index: 0.582)." (PMID 33685417, 2021). "Recently, several inflammation-based biomarkers (e.g., albumin, CRP, NLR and PLR) have been associated with treatment outcomes in primary operable tumours." (PMID 34056114, 2021).
tumor (continued). "which focused on sunitinib response found that high CRP was correlated with superior tumor size reduction in metastases only in tumors that were <20mm before treatment." (PMID 34512646, 2021). "The TNR-C includes CRP, pathologic T score, lymph node density, resection margins, age, and tumor size; as TNR-C score increases, both CSS and OS decrease." (PMID 34512646, 2021). "Here, we demonstrate, for the first time, CRP's ability to enhance IgG-mediated phagocytic and cytotoxic responses toward opsonized erythrocytes and tumor cells through FcγRs." (PMID 33790888, 2021). "In univariate analysis, CRP, Child–Pugh grade, tumor diameter, vascular invasion, tumor stage, degree of differentiation, intraoperative transfusion, PNI, and NLR were significant predictors of OS (p < 0.05)." (PMID 35155212, 2021). "HGC integrates both into a preoperative staging system, by combining C-reactive protein (CRP), albumin, and disseminated tumor cells (DTC) in the bone marrow." (PMID 34885052, 2021). "Meanwhile, the present study demonstrated that patients with a high lymphocyte-to-CRP score had more advanced tumor phenotypes." (PMID 33507925, 2021). "After prospective validation of the predictive potential of early CRP kinetics in mRCC and possibly in additional tumor subtypes, we propose early CRP kinetics as a promising on‐treatment biomarker for stratifying our patients in the era of immuno‐oncology." (PMID 34925829, 2021). "These later data suggest that further studies are needed to determine if the anti-tumor activities of CRP are mediated through effector cells other than macrophages." (PMID 34552600, 2021). "CRP plays a role in tumor inflammation, while MCV indicates the level of host nutrition among miscellaneous preoperative indicators." (PMID 34221966, 2021). "In hepatic IPTs, although inflammatory markers, including C-reactive protein and leukocyte count, and liver enzymes are sometimes elevated, tumor markers are usually normal." (PMID 33913027, 2021). "CRP levels were determined by immunoturbidimetry and classical tumor marker levels (CEA and CA 19-9) and were measured using chemiluminescent microparticle immunoassay (CMIA)." (PMID 34204490, 2021). "Several attempts have been made to investigate the possible risk factors for survival which suggested several possible risk factors as NLR, CRP/Alb, PLR, and tumor thrombosis of IVC and tumor stage." (PMID 34512814, 2021). "ROC curves were constructed, and the AUCs of CRP, fibrinogen, and tumor size in the prediction of an increased MIB-1 labeling index (≥6%) were determined." (PMID 34298854, 2021). "A fitting model was presented with a nomogram to predict the prognosis of HCC patients using serum CRP level, tumor-infiltrating TAMs and TANs." (PMID 35070979, 2021). "In multivariable analysis, baseline CRP level (p=0.016) and tumor response (p=0.021) were independently prognostic of OS." (PMID 34900709, 2021). "CRP-PR components were predicted to exert their therapeutic effect on the tumor signaling pathway, PI3K-Akt signaling pathway, MAPK signaling pathway, and estrogen signaling pathway." (PMID 33953786, 2021). "It has been reported that interaction between CRP and Fcγ receptor I facilitate tumor cell metastasis in breast cancer." (PMID 33013829, 2020). "The diagnostic cut-off value with respect to CRP for EOC was 9.8 mg/L, and high-level CRP was correlated with stage and tumor size of EOC." (PMID 33208875, 2020). "Subsequent multivariate analyses revealed that tumor size, pretreatment CRP, tumor histology and surgically tolerable physical condition were significantly correlated with OS (P < 0.05)." (PMID 32383730, 2020). "The highly structural homology between SAP and CRP suggests that SAP has the potential to mediate tumor progression through the Fcγ receptor." (PMID 33013829, 2020). "Analysis of the tumor tissue of these patients revealed that PD-L1 positive tumors were exclusively in the high CRP group with worse prognosis." (PMID 32646072, 2020).
tumor (continued). "It was of interest that tumour site appeared to have an impact on pre-iron infusion iron status defined by CRP and ferritin in this protocol." (PMID 32537137, 2020). "Furthermore, Ki-67 tumour expression was significantly correlating with blood CRP levels at diagnosis of MPE suggesting that tumours with high proliferation rate may be more likely to cause an acute phase response (as reflected by CRP)." (PMID 32238865, 2020). "We also reported that the earlier the stage, the smaller the tumor, and the higher the proportion of high-level CRP were of great significance in the diagnosis of EOC." (PMID 33208875, 2020). "CRP, an acute-phase protein that is synthesized in the liver along with other inflammatory cytokines, has been reported to possibly lead to tumor progression by inducing the production of inflammatory cytokines and chemokines." (PMID 33105743, 2020). "The median CRP levels were significantly higher in patients ≥60 years and in cases with tumor size ≥3 cm or with G3 grading." (PMID 32423000, 2020). "The host immune response to tumor growth can also include inflammation and an increase in serum CRP." (PMID 33121520, 2020). "During the process of tumor formation, the inflammatory cytokines produced by the tumor microenvironment stimulate hepatocytes, leading to the elevated level of serum CRP." (PMID 33364190, 2020). "Tumor grade, serum CRP, and IL-6 levels in patients exhibiting a high expression of both IL-6 and IL-6R were high." (PMID 32138303, 2020). "Results showed that among these clinical correlations, high levels of CRP were significantly correlated with tumor size and pathologic staging." (PMID 33208875, 2020). "For instance, Peter and colleagues observed a significant relationship of an elevated CRP level with advanced tumor stage, nodal status and overall survival in a cohort of 261 HNSCC patients." (PMID 32182693, 2020). "As the tumor growth, large amounts of inflammatory cytokines, especially interleukins-1 and -6 are produced to stimulate hepatocytes to produce more CRP." (PMID 32884743, 2020). "These outcomes explained our results that elevated CRP levels are associated with LNM, high tumor stage, and worse prognosis, including CSS, PFS, and OS." (PMID 33201589, 2020). "After return to the inflammatory tumor microenvironment, CRP is able to dock on the surface of the tumor cells, which are thereby marked for subsequent lysis by the host’s immune system." (PMID 31936329, 2020). "Optimal cut-offs in regard to association with OS and DSS were calculated at ≥0.2 mg/dL for high versus low CRP and ≥3.0 cm for small versus large tumor size." (PMID 32423000, 2020). "Considered together, an increased mGPS score, which means elevated CRP and/or reduced Alb, is considered to lead to tumor progression and a worse prognosis in patients treated with ICIs." (PMID 32441463, 2020). "Multiple studies have shown that plasma levels of C reactive protein (CRP) increase during tumor proliferation and several relations have been evaluated, CRP-survival relationship, CRP-response therapy, CRP-inflammation." (PMID 32855975, 2020). "An elevated CRP gives an upregulation of the vascular endothelial growth factor, which promotes the growth and proliferation of tumours." (PMID 33028394, 2020). "Women presented with higher tumor stages (p = 0.026); men had significantly higher hemoglobin (p = 0.037) and tryptophan concentrations (p = 0.031), and tended to have higher CRP concentrations (p = 0.062) and neutrophils counts (p = 0.064) compared to women." (PMID 33053619, 2020). "As a novel inflammation-based prognostic indicator, the CRP to albumin ratio (CRP/Alb) has been shown to demonstrate excellent prognostic incentives in various tumor destinations." (PMID 32566124, 2020). "Conversely, in this study, the median tumor size was 3.5 cm, bile duct invasion was observed in 48%, and the median CRP level was 0.12 mg/dL." (PMID 32856868, 2020).
tumor (continued). "In conclusion, we determined that the serum sPD‐L1 level was associated with the presence of liver metastasis and inflammatory markers such as CRP and was weakly correlated with tumor PD‐L1 expression." (PMID 33108686, 2020). "CRP can enter the tumor microenvironment through circulation and interact with various autologous and external ligands by binding as complex, which can in turn play a key role in activating or inhibiting tumor-associated macrophages." (PMID 33364190, 2020). "Targeted lowering of CRP should simultaneously allow for the maturation of tumor-reactive dendritic cells, which in turn would stimulate tumor-reactive T cell responses." (PMID 33633738, 2020). "Increasing CRP and GPS were significantly associated with greater tumor size and tumor stage as demonstrated in literature." (PMID 31936329, 2020). "Investigators previously found that levels of CRP were significantly elevated in blood of patients with tumors, and that the increase was correlated with tumor differentiation, tumor metastasis, and postoperative survival rate." (PMID 33208875, 2020). "There were significant differences regarding present illness (tumour), CRP (mg/dL), albumin (mg/dL), number of catheterizations catheterization times, total unused time (locked time), insertion anatomical site, dominant vein, and hyperosmotic solution." (PMID 32005839, 2020). "Our study revealed that serum levels of CXCL-8, similarly to those of the classical tumor marker and CRP, were significantly higher in CRC patients in comparison to the healthy controls." (PMID 32192002, 2020). "In this study, we further explored the promoting role CRP-SAA played in angiogenesis by activating tumor-inflammatory responses and inducing vascular network." (PMID 33364190, 2020). "C-reactive protein (CRP) is increased in PCa patients due to the systemic inflammatory response to the tumor, and tumor necrosis factor-α (TNF-α) is an upregulating factor of CRP." (PMID 32784500, 2020). "In the present paper we demonstrated that serum CXCR4 and CXCR2 were significantly elevated in PC patients compared to healthy controls, similarly to the classical tumor marker and CRP." (PMID 32867211, 2020). "Additional factors that were typically adjusted for included gender, age, smoking, body mass index, co-morbidities, C-reactive protein, primary tumour location, stage and grade." (PMID 33213430, 2020). "For example, CRP, together with inflammatory cells and mediators, creates a pro-neoplastic environment for tumor growth by inducing DNA damage and promoting angiogenesis." (PMID 33614510, 2020). "Variables with P-values < 0.05 in univariate analysis were included in our logistic regression models including demographic factors (sex, age, and smoking history), inflammatory factors (CRP or ferritin), and tumor markers (CEA or AFP)." (PMID 33123542, 2020). "Potential prognostic values have been shown by pretreatment serum inflammatory indicators like the neutrophil-to-lymphocyte ratio (NLR), lymphocyte-to-monocyte ratio (LMR), the C-reactive protein (CRP), and albumin (Alb) levels in some neoplasms." (PMID 33101044, 2020). "On multivariate analyses, tumor size, pretreatment C-reactive protein (CRP) value, histology and pretreatment physical state were significantly associated with OS." (PMID 32383730, 2020). "There were significant differences between the intervention and control groups in present illness (tumour), CRP, albumin, dressing films, level of nurse experience, number of catheterizations catheterization times”, and hyperosmotic solutions." (PMID 32005839, 2020). "Prospective studies have provided consistent results in the predictive value of CRP in neoplastic disease proving high sensitivity and specificity." (PMID 32855975, 2020). "There is also evidence suggesting that CRP is not only a marker of inflammation but also plays an active role in regulating the tumor microenvironment and tumor cell growth and survival." (PMID 33023215, 2020).
tumor (continued). "CRP is a significant marker of inflammation that is known to represent a critical component of tumor development and progression." (PMID 33023215, 2020). "In univariate analyses, SUVmax, tumor size, histology, pretreatment CRP and the reason for referral to SBRT were correlated with OS, with P values <0.15." (PMID 32383730, 2020). "According to the univariate analysis, high CRP (P = 0.032), tumor location (rectum) (P = 0.005), and low GNRI (P = 0.019) were significantly correlated with the complications." (PMID 32612136, 2020). "Nevertheless, diagnostics concerning a possible secondary bacterial infection are indicated in patients with tumor and high CRP values." (PMID 32434519, 2020). "Chronic activation of the IL-6/JAK/STAT pathway in the tumor and its microenvironment produces a deregulated inflammatory cascade at cellular and systemic levels (increased C-reactive protein, neutrophil counts and decreased albumin)." (PMID 32145060, 2020). "Immunohistochemistry shows a typical staining of tumour hepatocytes using antibodies against SAA or CRP." (PMID 32464711, 2020). "A study published in 2007 investigated the molecular mechanism of CRP in HCC cells in vitro, and concluded that CRP is highly expressed in tumor tissues, and also promotes invasion and metastases in HCC cell lines." (PMID 33256656, 2020). "From a consecutive series of 1750 operable LC patients, 68 never-smokers patients with high or low inflammatory profiles given by CRP levels were selected with a 1:1 matching design for age, gender, and tumor stage." (PMID 32646072, 2020). "The chemotherapeutic effects of EGCG significantly shrank tumors and reduced lipid peroxidation, leukocytosis, and C-reactive protein (CRP) as a predictor of tumor progression from cisplatin-induced nephrotoxicity." (PMID 33113766, 2020). "Each of these gene activations leads to the overexpression of the proteins of the acute inflammatory phase including SAA (serum amyloid protein) and CRP (C‐reactive protein), by tumour hepatocytes." (PMID 32464711, 2020). "Thus, circulating CRP levels reflect the magnitude of inflammation in the microenvironment that is favorable to tumor development and, particularly the levels measured at diagnosis, are associated with larger tumor size, lower tumor grade, and presence of metastasis." (PMID 33614510, 2020). "The three groups were statistically significant, and the proportion of high-level CRP in the group with tumor size ≤ 5 cm was the highest." (PMID 33208875, 2020). "In contrast, high NLR values have shown a positive correlation with tumor stage, tumor growth and the level of common inflammatory markers such as C-reactive protein (CRP), the plate-to-lymphocyte ratio (PLR), and the monocyte-to-lymphocyte ratio (MLR)." (PMID 32488850, 2020). "The presence of a positive significant relationship between IgM anti-GM1 level and IL-8 and CRP in our study justified our statement regarding the involvement of these antibodies in tumour proliferation by stimulating inflammation." (PMID 32855975, 2020). "CRP can increase vascular growth factors levels and interleukins in the peripheral blood, thereby promoting the formation of tumor blood vessels." (PMID 31312573, 2019). "Piwi-like 1 positivity distinguishes between prognostic groups within patients who suffer from tumors of high Fuhrman grade, high tumor stage, distant metastasis and those with high pre-operative CRP levels." (PMID 30741998, 2019).